INS (insulin)
Diseases named in the same sentence as INS in open-access papers (continued):
Sharing a sentence is not in itself a finding about the gene and the disease.
Glucose intolerance (continued). "In line with this, whole‐body deletion of ATF6 impaired glucose intolerance and blunted insulin secretion, whereas ATF6 induction improved β cell insulin secretion and viability under ER stress conditions." (PMID 37303813, 2023). "It was found that stroke rats developed glucose intolerance on days 1 and 2 after cerebral ischemic injury, and fasting blood insulin levels and insulin resistance index were higher in stroke rats than in the sham group." (PMID 36950100, 2023). "TCDD-exposed male offspring were also hypoglycemic at weaning and displayed modest, although transient, glucose intolerance and reduced glucose-stimulated plasma insulin levels shortly after TCDD exposure ceased." (PMID 37115651, 2023). "Chronically, this leads to insulin hypersecretion and glucose intolerance; TH directly stimulates pancreatic insulin secretion." (PMID 37841407, 2023). "Genetic or pharmacological interference with major platelet adhesion mechanisms consistently resulted in a reduction of insulin secretion and thus glucose intolerance." (PMID 37490001, 2023). "This notion is supported by the observation that, by 6 weeks of age, these mice exhibit glucose intolerance and reduced insulin secretion in response to glucose stimulation." (PMID 37610090, 2023). "In various preclinical models, BT2 is protective from glucose intolerance, insulin insensitivity, triglyceride accumulation, and hepatic inflammation similarly to DNP derivatives or Bam15." (PMID 37645724, 2023). "The predominant mechanism responsible for glucose intolerance after administration of GCs is reduced insulin sensitivity." (PMID 36701733, 2023). "Wfs1‐knockout mice were developed, which exhibit enhanced ER stress, impaired insulin processing and regulation of insulin secretion and develop progressive glucose intolerance and increased pancreatic beta cell death." (PMID 37440664, 2023). "On the other hand, it has been shown that Spiro administration counteracted western diet-induced glucose intolerance, IR, and impaired insulin metabolic signaling in the soleus in mice." (PMID 37108574, 2023). "Recently, it has been demonstrated that spironolactone administration inhibited western diet-induced glucose intolerance, and IR, and impaired insulin metabolic signaling in the soleus, which is rich in oxidative fibers, in mice." (PMID 37108574, 2023). "Quinoa added to the cafeteria diet reduced body weight and improved glucose intolerance, hepatic insulin signaling, and microvesicular steatosis." (PMID 37970433, 2023). "Mn supplementation improves glucose intolerance and prevents diet-induced diabetes by increasing insulin secretion and the expression of IGFR and IGF-1 in the hypothalamus, as well as increasing the expression of MnSOD." (PMID 38132161, 2023). "In the context of high-fat diet, Pctp−/− protects mice from diet-induced insulin and glucose intolerance as indicated by glucose tolerance test and increases in phosphorylation of important mediators of insulin signaling." (PMID 37173315, 2023). "Correlating with their glucose intolerance, ΔIl33Pericytes male mice had significantly lower serum insulin levels after a glucose challenge than control mice." (PMID 36967785, 2023). "Further, pancreatic β‐cells were investigated since their failure to stimulate the secretion of insulin is seen in glucose intolerance." (PMID 37970433, 2023). "Is the reduction in HK2 in obese mice and patients sufficient to contribute to systemic insulin insensitivity and glucose intolerance?" (PMID 36920797, 2023). "The activation of the renin–angiotensin–aldosterone system reduces potassium concentrations in the body, thereby inhibiting insulin release and increasing glucose intolerance." (PMID 37107973, 2023). "Glucose intolerance is a component of many factors, including increased body fat mass, decreased physical activity, medications, concomitant diseases, defects in insulin secretion, and decreased liver sensitivity that inhibit glucose output." (PMID 36983369, 2023).
Glucose intolerance (continued). "In diabetic rats, ellagic acid decreases blood glucose levels and increases the levels of serum insulin, mitigates glucose intolerance, and stimulates insulin secretion." (PMID 37999220, 2023). "The cafeteria diet resulted in increased body weight, glucose intolerance, impaired hepatic insulin signaling, microvesicular steatosis, and reduced β‐cell insulin immunoreactivity." (PMID 37970433, 2023). "Glucose intolerance in βp65KO mice was due to a severely blunted glucose-stimulated insulin secretory response." (PMID 37311878, 2023). "6JRccEnv mice, especially males, presented with glucose intolerance, elevated plasma insulin levels and phosphorylation of insulin signalling markers." (PMID 37531359, 2023). "When Ogfr was ablated in adipocytes, the mice tended to accumulate lipids and display reduced thermogenic capacity, and developed more severe glucose intolerance and insulin insensitivity after chronic feeding with HFD." (PMID 39872016, 2023). "In line with this, previous studies demonstrated the induction of glucose intolerance by endocannabinoid agonists and an improvement in insulin sensitivity by CB1 antagonists." (PMID 37762099, 2023). "There is a significant inverse correlation between testosterone and fasting glucose and insulin levels as well as glucose intolerance." (PMID 36814583, 2023). "Studies with animal models showed that selective CB2 receptor agonists modulate food intake, reduce weight gain, relieve glucose intolerance, and enhance insulin sensitivity." (PMID 38139344, 2023). "HFD-fed EECΔCol mice displayed even greater glucose intolerance, as well as a blunted rise in insulin and GLP-1 in response to glucose." (PMID 37461519, 2023). "Mice exposed to air pollution particles via gavage exhibited glucose intolerance and impaired insulin secretion from approximately 3–4 months onwards." (PMID 36895000, 2023). "Elevated ETV5 levels impair insulin secretion and lead to glucose intolerance, indicating the key role of the CRL4COP1/DET1-ETV5 axis in nutrient-induced insulin secretion (upper)." (PMID 36872348, 2023). "When administered into normal mice, CMPF blunts glucose-stimulated insulin release, resulting in glucose intolerance." (PMID 38229396, 2023). "We found that murine models of human CPVT with mutant leaky RyR2 also quite unexpectedly displayed glucose intolerance secondary to impaired insulin secretion due to leaky RyR2 channels in their pancreatic β cells." (PMID 36647824, 2023). "This study demonstrated that the Western diet associated with ovariectomy promotes increased fat mass, basal glucose, glucose intolerance, and plasma insulin in female ApoE KO mice." (PMID 37372993, 2023). "Virgin α-cell null mice exhibit better glycemic control in response to glucose challenge, but during pregnancy, α-cell null mice develop severe glucose intolerance due to significantly reduced glucose-stimulated insulin secretion." (PMID 38229396, 2023). "Our data showed that reactivation of hepatocyte TLR4 exacerbated alcohol-induced glucose intolerance and decreased insulin signaling." (PMID 36979389, 2023). "Mice carrying a bone marrow‐specific deletion of GPVI displayed glucose intolerance, and impaired insulin secretion but unaltered insulin sensitivity compared to controls." (PMID 37490001, 2023). "Genetic overexpression of MitoNEET, which is a mitochondrial outer membrane iron-sulfur protein, induced PARKIN and PARKIN-dependent mitophagy, which led to decreased β-cell mass, impaired insulin release, and glucose intolerance." (PMID 37653033, 2023). "The present study showed that all TMD types decreased glucose intolerance, mainly by enhancing insulin sensitivity." (PMID 37569228, 2023). "Several in vivo studies found that Mn deficiency caused glucose intolerance and reduced insulin secretion, manifested by decreased circulating IGF-1 and insulin, and increased IGFBP3." (PMID 38132161, 2023).
Glucose intolerance (continued). "Selective deletion of the leptin receptor in tanycytes blocks leptin entry into the brain, leading to glucose intolerance because of reduced insulin secretion, potentially through an altered sympathetic nervous system." (PMID 37761031, 2023). "In WT mice, OFS supplementation significantly reduced body weight gain, adiposity and fasting insulin levels and improved fasting glucose as well as glucose intolerance." (PMID 35697422, 2023). "Consistent with our analysis of the preventive effect of DLPC, we found that DLPC-treated DIO mice showed improved glucose intolerance and insulin sensitivity, as well as decreases in the serum levels of T-CHO and LDL-C." (PMID 38036537, 2023). "Glucose intolerance was intensified by the end of the treatment, with no changes in basal glycemia and plasma leptin and insulin levels." (PMID 37616199, 2023). "chα-IAPP-O reduced the progression of glucose intolerance and improved glucose-stimulated insulin secretion compared to vehicle after 8, 15, and 24 weeks of treatment with steady state plasma drug concentrations around 90 μg/ml." (PMID 37813862, 2023). "To investigate the basis of glucose intolerance in animals exposed to cafeteria diet, we examined the mRNA expression of five components of the insulin signaling pathway in the liver." (PMID 37970433, 2023). "We found that glucose intolerance and reduction in glucose-stimulated insulin secretion developed in βKO mice compared with the control subjects." (PMID 37277555, 2023). "Here, we report that selective deletion of Trpm7 in β cells disrupted insulin secretion and led to progressive glucose intolerance." (PMID 36574297, 2023). "Consistently, ablation of VAPB in mice led to downregulation of IRS-1, suppression of insulin signaling, and glucose intolerance." (PMID 37528084, 2023). "The VAI correlated positively with fasting glucose intolerance, two-hour post-load glucose, fasting insulin, insulin overload (120′), HbA1c, and HOMA-IR." (PMID 38137483, 2023). "Since skeletal muscle is a main site of insulin-stimulated glucose uptake, decreased muscle mass can lead to decreased whole-body glucose disposal and, as a result, glucose intolerance." (PMID 37109166, 2023). "By using it, it was substantiated that the GLP-1RA liraglutide was effective in preventing the development of glucose intolerance, improving insulin and glucagon secretion control, and reducing ER stress in Langerhans islets in Wfs1−/− rats." (PMID 37333802, 2023). "Since the first description of mitochondrial dysfunction in the context of glucose intolerance more than 40 years ago, mitochondria have been placed as a key organelle in the development of peripheral insulin resistance." (PMID 37153211, 2023). "In another study, we found that murine models of human CPVT exhibited glucose intolerance and impaired insulin secretion." (PMID 36647824, 2023). "Dex treatment was trending to induce glucose intolerance and significantly elevated plasma insulin levels." (PMID 37253782, 2023). "The supplementation of manganese has been shown to enhance insulin secretion and ameliorate glucose intolerance in diabetic mice." (PMID 37887373, 2023). "Liver-specific downregulation of KDM6B resulted in intrinsic mitochondrial β-oxidation defects, which further led to hepatic steatosis and insulin and glucose intolerance." (PMID 37185761, 2023). "We observed that WD + STZ mice exhibited glucose intolerance and impaired insulin secretion during fasting and post-glucose challenge, which are key features of T2D." (PMID 37885804, 2023). "Conversely, animals in which BCL-XL expression surpassed a 10-fold increase displayed severe glucose intolerance, as well as impaired ex vivo insulin secretion and intracellular Ca2+ responses." (PMID 36982731, 2023). "It has been shown that the ablation of Mfn2 in a mice model results in glucose intolerance, increased hepatic gluconeogenesis, impaired insulin signalling, as well as the development of ER stress." (PMID 37020593, 2023).
Glucose intolerance (continued). "For instance, E. royleana stem extract decreased fasting BG (FBG) and ameliorated glucose intolerance in diabetic rats, and E. helioscopia alleviated BG and insulin in sucrose-fed rats." (PMID 37397470, 2023). "While mice constitutively expressing Beclin1, leading to continuously active autophagy, experience improved insulin sensitivity, they have impaired insulin secretion leading to glucose intolerance when fed on a high-fat diet." (PMID 37759604, 2023). "Adipsin KO mice display glucose intolerance due to reduced insulin secretion, and their isolated islets exhibit reduced GSIS." (PMID 37761031, 2023). "Significant differences of glucose intolerance and insulin sensitivity were exhibited at the middle and late stage of pregnancy, suggesting the successful establishment of HFD-induced GDM model." (PMID 36803098, 2023). "Taken together, these tests suggest eTRF results in males who experience glucose intolerance and insulin sensitivity, whereas females are more resilient to glycemic changes after gestational eTRF." (PMID 37808966, 2023). "LIRKO mice still showed obvious IR, severe glucose intolerance, and resistance to insulin’s ability to inhibit liver sugar production under the premise of normal insulin signal transduction in fat and muscle tissues." (PMID 36631836, 2023). "While both lung and gut exposure resulted in increased liver lipids, glucose intolerance and impaired insulin secretion was only observed in mice exposed to particles by gavage." (PMID 36895000, 2023). "Given that we cannot explain glucose intolerance in males via reduced insulin sensitivity, we next evaluated insulin secretion." (PMID 37808966, 2023). "The other metabolic phenotype observed in male 6JRccEnv indicated that sustained elevations in fasted basal insulin levels resulted in glucose intolerance." (PMID 37531359, 2023). "These pathologies are believed to lead to glucose intolerance, reduced insulin sensitivity, and weight gain." (PMID 37371762, 2023). "Two distinct metabolic profiles were identified, one in which low insulin levels resulted in impaired glucose clearance (6JCrl; both sexes) and the other, where sustained elevations in fasted basal insulin levels led to glucose intolerance (male 6JRccEnv)." (PMID 37531359, 2023). "Exposure of the liver to high fructose levels induces lipogenesis and TG buildup acceleration, which reduces insulin sensitivity and increases hepatic insulin resistance and glucose intolerance." (PMID 37752490, 2023). "Despite the striking increase in Ins2 mRNA, β‐DKO mice were characterized by lower body weight and glucose intolerance compared to control littermates, likely as a result of defective insulin release and consistent with recently published data." (PMID 37712288, 2023). "The WHO criterion assesses glycemic homeostasis by means of insulin levels, glucose intolerance and fasting glucose; only the latter was used in this analysis." (PMID 38232261, 2023). "Given that continuous MR has been previously demonstrated to effectively prevent the glucose intolerance and insulin insensitivity otherwise experienced by mice maintained on a high‐fat diet, we reasoned that IMR would result in similar protection." (PMID 35570387, 2022). "Ellagic acid has antidiabetic properties due to its effect on pancreatic β-cells, which promote insulin production and reduce glucose intolerance." (PMID 35845257, 2022). "CXCL14 is a chemokine secreted by BAT in response to thermogenic stimuli and M2 macrophage signaling, which can increase insulin action and mitigate systemic glucose intolerance." (PMID 35928901, 2022). "Others have shown that HFD worsens weight gain, glucose intolerance, changes in circulating glucose and insulin, and adiposity in AD transgenics." (PMID 35958733, 2022). "Taken together, these data suggest that ActRIIB-Fc treatment induces a modest glucose intolerance, perhaps due to slight insulin resistance." (PMID 35024891, 2022).
Glucose intolerance (continued). "T2D is especially characterized by glucose intolerance due to insufficient production of insulin in relation to IR24." (PMID 35987753, 2022). "These were associated with a significant increase in grafted β cell proliferation and blood insulin levels, resulting in improved glucose intolerance." (PMID 34987651, 2022). "Due to insulin and glucose intolerance, which raises lipogenesis and blood glucose levels, the glyphosate-treated groups showed significant increase in G6P and F1,6BP activity." (PMID 36552644, 2022). "We find that miR-21βKO mice develop glucose intolerance due to impaired glucose-stimulated insulin secretion." (PMID 35729232, 2022). "As reported, S6k1−/− mice exhibited hypoinsulinemia and glucose intolerance accompanied by decreased insulin secretion, which is mildly phenocopied by S6P−/− mice." (PMID 35879299, 2022). "Female Sprague Dawley neonates whose fathers were fed an HFD diet have impaired insulin secretion and glucose intolerance at adulthood." (PMID 35216239, 2022). "Inactivation of PI3K/Akt in β-cells has decreased insulin secretion and glucose intolerance through downregulating PDX-1." (PMID 35408495, 2022). "Vitamin A deficiency introduced during pregnancy produces rat pups with reduced glucose-stimulated insulin secretion and promotes glucose intolerance." (PMID 35458115, 2022). "Whole-body PCK2-/- mice display glucose intolerance and reduced insulin secretion in response to glucose and AA." (PMID 35997256, 2022). "Here, we showed that the Senp2-βKO mice exhibited impaired insulin secretion and glucose intolerance accompanied by decreased mitochondrial function and abnormal mitochondrial morphology." (PMID 35064188, 2022). "TLR2−/− mice demonstrated marked glucose intolerance and were also highly resistant to the hypoglycaemic effect of exogenous insulin at 7 months of age." (PMID 36555322, 2022). "The authors showed that glucose intolerance in offspring was attributed to impaired glucose‐stimulated insulin secretion by pancreatic islets beta cells." (PMID 35802824, 2022). "In both WT and eNOS+/− groups, HFD induces a progressive and marked glucose intolerance, with increased basal and post‐loading glycemia, as well as a reduction in insulin sensitivity at 8 and 16 weeks." (PMID 35986504, 2022). "This glucose intolerance is likely mediated by the reduced plasma insulin levels observed in the IL-6Ra KD mouse." (PMID 35470093, 2022). "Mice with double deletion of p66Shc and leptin were glucose intolerant like leptin knockout mice, but the double knockout mice showed a lesser degree of glucose intolerance and better insulin sensitivity." (PMID 36465704, 2022). "Phytosphingosine has been demonstrated to exhibit an effect on glucose intolerance, insulin sensitivity and decreasing cholesterol levels." (PMID 36557305, 2022). "In contrast, adenoviruses expressing FGF9 (Ad-FGF9) mediated FGF9 overexpression in the liver of DIO mice alleviated hepatic steatosis and improved the insulin sensitivity and glucose intolerance." (PMID 35517790, 2022). "Whereas, when fathers were fed a high fat diet for 10 weeks before mating, female (but not male) offspring had impaired pancreatic β-cell function, with increased bodyweight and glucose intolerance, and reduced insulin secretion." (PMID 36386900, 2022). "Eight weeks of aerobic exercise attenuated HFD-induced weight gain and glucose intolerance, and improved insulin sensitivity." (PMID 36145106, 2022). "We found that both male and female p20 rats show elevated blood glucose and insulin levels, low systemic insulin sensitivity, and glucose intolerance." (PMID 36224569, 2022). "β-cell-specific UCP2-overexpressing transgenic mice (βUCP2Tg) exhibited glucose intolerance and a reduction in insulin secretion." (PMID 35800776, 2022).